BDNF (brain derived neurotrophic factor)
Diseases named in the same sentence as BDNF in open-access papers (continued):
Sharing a sentence is not in itself a finding about the gene and the disease.
asthma (27 papers, 2006 to 2025). "In previous studies on BDNF rs11030101, a significant association with asthma was first identified, followed by subsequent studies primarily confirming associations in psychiatric disorders." (PMID 41300755, 2025). "The effects of BDNF gene polymorphisms on asthma susceptibility and severity have also been addressed and a possible association of BDNF gene variants with asthma severity has been reported." (PMID 39064540, 2024). "A recent study, showing higher amounts of mature BDNF in the sputum of patients with severe asthma in comparison to healthy subjects, has suggested a possible association of BDNF expression with asthma severity." (PMID 33114368, 2020). "It is possible that in patients with asthma, due to the complex pathophysiology of this disease, other factors predominantly influence BDNF plasma levels, masking the effect of the functional BDNF Val66Met polymorphism." (PMID 33114368, 2020). "On contrary, results in our cohort of asthma patients in the present study showed more robust linear association in the stratum comprising patients in the upper half of the BDNF levels." (PMID 29217995, 2017). "Further, as described in the introduction elevated BDNF levels seem related to chronic inflammation e.g. rheumatoid arthritis and asthma and are also associated with increased risk factors of cardiovascular diseases." (PMID 26011424, 2015). "The aim of this study was to analyze the possible association of BDNF gene polymorphism with susceptibility to asthma and disease severity." (PMID 23282800, 2010). "The main finding of our study is an association of rs2030324 BDNF polymorphism with asthma in our pediatric population." (PMID 23282800, 2010). "The main limitation of our study is a relatively small sample size in comparison to the other studies reporting on the role of BDNF polymorphism in asthma." (PMID 23282800, 2010). "In agreement with a pathogenic role in allergic asthma, elevated levels of NGF, BDNF and NT-3 have been detected in blood and locally in the airways in patients with asthma, a response that can be further augmented after allergen challenge." (PMID 16441896, 2006). "Polymorphisms in the BDNF gene are also associated with asthma." (PMID 40626045, 2025). "The BDNF Val66Met polymorphism has previously been associated with asthma in children of Chinese Han and Slovak origin; whereas a recent meta-analysis has suggested that the G allele of BDNF Val66Met polymorphism is potentially associated with asthma risk in Caucasians." (PMID 33114368, 2020). "Moreover, the causative effect of BDNF in the paradoxical loss of asthma control following unbalanced use of β2 agonists has been proposed." (PMID 29217995, 2017). "Interestingly, some chronic inflammatory disorders such as rheumatoid arthritis and asthma have been associated with elevated BDNF levels in the severe states." (PMID 26011424, 2015). "Our results suggest that genetic variation in the BDNF gene may contribute to asthma susceptibility in case of rs2030324 polymorphism and TTGC haplotype, however it does not influence asthma severity." (PMID 23282800, 2010). "Increased BDNF concentrations may underly the adverse effects of salmeterol monotherapy on airway responsiveness in asthma." (PMID 19237390, 2009). "It is noteworthy that BDNF expression is significantly elevated in the ASM of patients with asthma, suggesting its potential role in airway remodeling and hyperreactivity." (PMID 40034284, 2025). "Studies focused on BDNF in the context of asthma have emphasized its effects on airway smooth muscle and nerves." (PMID 40626045, 2025). "The relevance of BDNF lies in novel clinical findings indicating changes in this neurotrophin and function in a variety of disorders including neonatal and adult asthma, influenza (including COVID-19), sinusitis, and lung tumor." (PMID 39403060, 2024). "Contrary to the findings in AD, the topic of increased BDNF serum levels in asthma is controversial." (PMID 37047077, 2023).
asthma (continued). "Few researchers have also considered allergies a confounding feature due to the recent report of elevated BDNF levels in patients with allergic diseases, such as asthma." (PMID 37108250, 2023). "Another study recently reported a higher level of BDNF protein in neutrophil rich sputum from patients with asthma than in sputum from patients with lower neutrophil counts." (PMID 34771682, 2021). "Increased expression of BDNF has been observed in severe asthma, bronchial hyperresponsiveness, and inflammation, but to our knowledge, it has not been observed in food allergy." (PMID 33571165, 2021). "This is in contrast to the previously reported data suggesting BDNF as a potential biomarker for clinical severity of asthma in children." (PMID 33114368, 2020). "On the other hand, significantly and nominally higher plasma BDNF levels were observed in patients with aspirin-sensitive asthma and AERD, respectively." (PMID 33114368, 2020). "Further research is required to clarify the acute and long-term effects of respiratory tract infections on peripheral BDNF levels in the general population, and specifically, in asthma patients." (PMID 33114368, 2020). "On the other hand, asthma patients with a history of pneumonia (0.69 pg/mL, 0.48–0.92) had nominally lower plasma BDNF concentrations (p = 0.026) in comparison to asthma patients who had previously never developed pneumonia (0.95 pg/mL, 0.61–1.29)." (PMID 33114368, 2020). "It has also been shown that children with moderate and severe asthma had higher plasma BDNF levels than age-matched control subjects." (PMID 33114368, 2020). "More research is needed to define the role of BDNF in nasal polyps and aspirin sensitivity in asthma." (PMID 33114368, 2020). "In conclusion, our findings indicate that asthma patients have higher plasma BDNF levels than healthy subjects." (PMID 33114368, 2020). "Plasma BDNF concentrations were significantly higher (p < 0.0001) in asthma patients in comparison to the healthy subjects." (PMID 33114368, 2020). "Nevertheless, our data are in line with the report on increased BDNF levels in the serum, platelets, and plasma of asthma patients compared to the control group." (PMID 33114368, 2020). "Few reports in the literature up to this point have evaluated the possible influence of BDNF and NTRK2 polymorphic variants on serum and plasma BDNF levels in patients with asthma." (PMID 33114368, 2020). "Plasma BDNF concentrations, as well as BDNF and NTRK2 (TrkB gene) polymorphisms, were investigated in 120 asthma patients and 120 healthy individuals using enzyme-linked immunosorbent assay and polymerase chain reaction, respectively." (PMID 33114368, 2020). "Plasma BDNF concentrations were nominally higher (p = 0.025) in asthma patients with nasal polyps (1.12 pg/mL, 0.72–1.35) versus those without (0.81 pg/mL, 0.58–1.15)." (PMID 33114368, 2020). "Higher plasma BDNF levels were observed in asthma patients with aspirin sensitivity and aspirin-exacerbated respiratory disease." (PMID 33114368, 2020). "In our study, asthma patients with a history of pneumonia had nominally lower plasma BDNF concentrations in comparison to asthma patients who had never developed pneumonia." (PMID 33114368, 2020). "BDNF protein concentrations are upregulated in severe asthma patients and in those with airway hyperresponsiveness." (PMID 30658649, 2019). "Brain-derived neurotrophic factor (BDNF) was significantly downregulated in the asthma cohort following benralizumab treatment (FDR < 0.05), although the magnitude of change was modest (10% decrease post-treatment)." (PMID 30658649, 2019). "BDNF, a protein that positively relates to eosinophil counts in atopic dermatitis, was the only protein that was significantly decreased in the asthma cohort following benralizumab treatment." (PMID 30658649, 2019). "The main finding of the present study is that alteration of irisin/BDNF axis parallels the evolution of distress disorder in asthma." (PMID 29217995, 2017).
asthma (continued). "The ability of BDNF to induce airflow limitation and to promote airway hyperresponsiveness to histamine has been described in animal models of asthma as well as in asthma patients." (PMID 29217995, 2017). "Due to the abundance of clinical observations regarding the complex interplay between asthma and distress disorder we set out to assess the potential interaction between the irisin/BDNF axis and severity of distress disease in our asthma patient cohort." (PMID 29217995, 2017). "BDNF also has an important role in smooth muscle hypertrophy which contributes to persistent late phase of asthma." (PMID 24010817, 2013). "Given previous studies demonstrating upregulation of airway BDNF in asthma and allergic diseases these data suggest that prolonged BDNF exposure can contribute to enhanced ASM contractility via genomic effects." (PMID 22952960, 2012). "Accordingly, in diseases such as asthma, BDNF has the potential to enhance one cascade vs. the other to enhance [Ca2+]i or cell proliferation as we have previously shown." (PMID 22952960, 2012). "In patients with asthma, it was previously shown that elevated serum BDNF concentrations correlate with disease severity, whereas TGF-β1 concentrations were normal." (PMID 23245944, 2012). "Salmeterol monotherapy significantly increased systemic BDNF concentrations in patients with asthma, and these changes correlated with the deterioration of airway hyperresponsiveness." (PMID 23245944, 2012). "The relevance of such effects lies in the recent recognition that the levels of circulating and local BDNF, as well as receptor expression are increased in asthma." (PMID 22952960, 2012). "The neurotrophin brain-derived neurotrophic factor (BDNF) has recently been identified as a mediator of airway hyper-responsiveness in asthma." (PMID 19237390, 2009). "In this report, we investigate the effect of monotherapy with a LABA on BDNF concentrations and airway responsiveness in patients with asthma." (PMID 19237390, 2009). "In the present study, 14 days of treatment with salmeterol in patients with asthma led to a significant increase in platelet BDNF concentrations and this was correlated with changes in airway responsiveness." (PMID 19237390, 2009). "In conclusion, we show that unbalanced monotherapy with salmeterol in patients with mild asthma increases BDNF production and storage and that changes in AHR are associated with this effect." (PMID 19237390, 2009). "A comprehensive investigation into the mechanisms of BDNF may facilitate the development of novel therapeutic strategies aimed at improving the prognosis of patients with asthma and COPD." (PMID 40034284, 2025). "Additionally, it has also been observed that BDNF levels in bronchoalveolar lavage fluid (BALF) of asthma patients were elevated after provocation with allergens." (PMID 37047077, 2023). "BDNF may contribute to normal lung function and immune response and may serve as a potential peripheral biomarker for asthma, especially that is aspirin-sensitive." (PMID 35600600, 2022). "Neurotrophins, including NGF, BDNF, and neurotrophin 3, are increased in asthma and these factors may have important roles in neuroplasticity." (PMID 34557110, 2021). "Moreover, further research is warranted to better understand the role of peripheral BDNF levels, as well as BDNF and NTRK2 (TrkB gene) polymorphisms, in adult asthma." (PMID 33114368, 2020). "We also examined the relationship between plasma BDNF levels and asthma severity." (PMID 33114368, 2020). "Interestingly, we observed the opposite trend of increased plasma BDNF levels in asthma patients with nasal polyps, as well as in those with aspirin sensitivity." (PMID 33114368, 2020). "Overall, our results suggest that BDNF may be a useful peripheral blood biomarker of asthma in general, and especially for asthma with aspirin sensitivity." (PMID 33114368, 2020).
asthma (continued). "Our results in asthma patients are in agreement with the data showing that BDNF Val66Met variants do not affect the BDNF serum levels in children with asthma." (PMID 33114368, 2020). "This suggests that serum irisin level is associated with processes that lead to disease-related impairment of psycho-social function among asthma patients, an effect that is more pronounced if higher serum irisin concentration is accompanied with higher serum BDNF level." (PMID 29217995, 2017). "Limited number of reports are available concerning the change of serum BDNF levels in asthma." (PMID 29217995, 2017). "Thus, the aim of the present study was to quantify the serum irisin and BDNF concentrations in order to investigate the possible link between the irisin/BDNF axis and distress disorder in an asthma patient cohort." (PMID 29217995, 2017). "Furthermore, BDNF levels correlate with disease severity in asthma, atopic dermatitis, and allergic rhinitis." (PMID 26442233, 2015). "BDNF has been found to play a role in the late phase of asthma, and has been reported to be involved in the infiltration of eosinophils, which are known for their persistent activity in asthma, into the lungs." (PMID 24010817, 2013). "Thus, since therapy with the LABA salmeterol was shown to increase BDNF concentrations in serum of patients with asthma, it cannot be excluded that the difference between patients and controls is attributable to LABA therapy." (PMID 23245944, 2012). "We hypothesised that the expression of BDNF and TGF-β1 and the association with lung function might differ between asthma and COPD." (PMID 23245944, 2012). "Importantly, increased BDNF and receptor expression has been found in blood, tissue and lung lavages of patients with asthma and chronic bronchitis, suggesting a role for BDNF in altered airway structure and function during inflammation." (PMID 22952960, 2012). "We, therefore, hypothesise that augmented BDNF concentrations explain some of the adverse effects of β2-agonists in asthma." (PMID 19237390, 2009). "In addition, we investigated the plasma BDNF concentrations in various asthma phenotypes." (PMID 33114368, 2020). "A number of studies thus far have sought to investigate the role of BDNF in the airways by assessing its concentration locally and in the peripheral circulation, as well as by determining the association between selected polymorphisms in the BDNF and NTRK2 (TrkB) genes and the development of asthma." (PMID 33114368, 2020). "Therefore, plasma BDNF levels in asthma patients are likely influenced by a complex interaction between environmental factors and genetic predisposition, and might be primarily related to the pathophysiology of the disease." (PMID 33114368, 2020). "Altered BDNF regulation may also contribute to adverse effects of β2-agonists in asthma." (PMID 23245944, 2012). "Therefore, some of the beneficial effects of ICS in a combination with LABA in asthma might be related to a suppression of LABA-induced BDNF overexpression." (PMID 19237390, 2009). "However, it is also conceivable that platelet BDNF plays a genuine role in asthma." (PMID 19237390, 2009). "Thus, the correlation between the changes in AHR and the changes in BDNF concentrations suggests that BDNF might indeed contribute to the development of AHR in asthma and to some of the adverse effects of a salmeterol monotherapy." (PMID 19237390, 2009). "Brain-derived neurotrophic factor (BDNF) is a neural plasticity molecule that is increasingly recognized for its role in airway pathophysiology, including diseases like asthma." (PMID 40626045, 2025). "In human lungs, increased BDNF levels have been observed in sputum and bronchoalveolar lavage (BAL) fluid from patients with asthma." (PMID 39064540, 2024). "The BDNF Val66Met genotype distributions were in HWE for both the control group (p = 0.38) and asthma patients (p = 0.26)." (PMID 33114368, 2020).
asthma (continued). "However, the same group of authors later reported that BDNF Val66Met polymorphism in a haplotype (TTGC) with three other BDNF polymorphisms may contribute to asthma susceptibility, but does not influence asthma severity." (PMID 33114368, 2020). "We hypothesized that plasma BDNF concentration would be significantly altered in asthma patients compared to healthy subjects, while BDNF Val66Met and NTRK2 rs1439050 polymorphisms would be associated with asthma, disease severity, and certain asthma phenotypes." (PMID 33114368, 2020). "We demonstrate for the first time that, in contrast to asthma, COPD is characterised by increased concentrations of both BDNF and TGF-β1 in serum." (PMID 23245944, 2012). "This clinical study is the first to show that, in contrast to asthma, COPD is characterised by an elevation of both BDNF and TGF-β1 in serum." (PMID 23245944, 2012). "Taken together, we show that, in contrast to asthma, COPD is characterised by elevated concentrations of both BDNF and TGF-β1 in serum." (PMID 23245944, 2012). "NT-3 also might play a role in allergic asthma as levels in BALF of asthma patients after allergen provocation have been found to be elevated, which has previously also been described for NGF and BDNF." (PMID 37047077, 2023). "The concentration of BDNF in plasma was not significantly correlated with the BMI of asthma patients (p = 0.17, r = 0.13) or healthy subjects (p = 0.54, r = 0.06)." (PMID 33114368, 2020). "According to our results, plasma BDNF levels cannot be used to distinguish severe from non-severe disease or between the different asthma phenotypes (allergic versus non-allergic, T2-high versus T2-low, or non-eosinophilic versus eosinophilic asthma)." (PMID 33114368, 2020). "Plasma BDNF concentration was not influenced by NTRK2 rs1439050 polymorphism in both healthy subjects and asthma patients." (PMID 33114368, 2020). "Plasma BDNF levels were significantly higher in both non-severe (0.91 pg/mL, 0.50–1.22; p = 0.005) and severe asthma patients (0.88 pg/mL, 0.61–1.29; p = 0.0004) compared to the control group (0.56 pg/mL, 0.45–0.92)." (PMID 33114368, 2020). "Brain-derived neurotrophic factor (BDNF) and its tropomyosin-related kinase B (TrkB) receptor might contribute to normal lung functioning and immune responses; however, their role in asthma remains unclear." (PMID 33114368, 2020). "A positive correlation (p = 0.023, r = 0.21) was observed between plasma BDNF concentration and duration of disease in asthma patients, although this result was not significant after correcting for multiple testing." (PMID 33114368, 2020). "To date, BDNF as a potential blood biomarker in asthma has not yet been studied in a Croatian population." (PMID 33114368, 2020). "In contrast to the control group, plasma BDNF concentrations in the asthma patients were not affected by the BDNF Val66Met genotype, allele, or carrier distribution." (PMID 33114368, 2020). "By regulating BALF NGF, TARC and serum BDNF levels, XQLT may control allergic inflammation and eosinophil infiltration in both the early and the late phases of asthma." (PMID 24010817, 2013). "The effects of BDNF are most apparent in the late phase of asthma, rather than in the acute phase, and BDNF has also been reported to affect the infiltration of eosinophils into the lungs." (PMID 24010817, 2013). "Although BDNF and TGF-β1 are stored in the same platelet granule, serum TGF-β1 concentrations are not significantly different from controls in patients with mild to moderate asthma." (PMID 23245944, 2012). "Thus, it appears that, in contrast to asthma, COPD is characterised by a concomitant increase of both platelet-mediators BDNF and TGF-β1." (PMID 23245944, 2012). "Of note, in this subgroup of patients, a significant negative correlation between FEV1 and serum BDNF was found, which was comparable to the findings in asthma." (PMID 23245944, 2012).